ZNF471 (zinc finger protein 471)
Description:
May be involved in transcriptional regulation.
Synonyms: ERP1; KIAA1396; Z1971; Zfp78
Tractability: PROTAC: ubiquitination databases record sites on it.
Gene: Protein-coding gene on chromosome 19 (56,507,731 to 56,530,221, forward strand). Ensembl gene ENSG00000196263.
Subcellular location: Nucleus
Subcellular location (Human Protein Atlas): Nucleoplasm
Pathways (Reactome):
Gene expression (Transcription): Generic Transcription Pathway
Gene Ontology:
Molecular function: protein binding; DNA-binding transcription factor activity, RNA polymerase II-specific; RNA polymerase II cis-regulatory region sequence-specific DNA binding
Biological process: regulation of transcription by RNA polymerase II; regulation of DNA-templated transcription
Cellular component: nucleoplasm; nucleus
Genetic constraint (gnomAD): Loss-of-function variants: 8 observed, 12.73 expected, observed/expected ratio (o/e) 0.63, 90% interval 0.37 to 1.13. The upper end of that interval is the gene's LOEUF score, 1.13, which puts it in group 4 of 6, group 1 being the genes least tolerant of losing a copy. Missense variants: 660 observed, 774.18 expected, observed/expected ratio (o/e) 0.85, 90% interval 0.8 to 0.91. Synonymous variants: 217 observed, 246.63 expected, observed/expected ratio (o/e) 0.88, 90% interval 0.79 to 0.99.
Homologues: Orthologues: chimpanzee ZNF471 (99% identical), macaque ZNF471 (98% identical), pig ZNF471 (80% identical), rabbit ZNF471 (67% identical). Paralogues in human: ZNF470 (63% identical), ZFP28 (58% identical), ZNF658 (47% identical), ZNF33B (45% identical), ZNF484 (44% identical), ZNF7 (44% identical), ZNF568 (44% identical), ZNF879 (44% identical), ZNF595 (43% identical), ZNF28 (43% identical), ZNF585B (43% identical), ZNF605 (43% identical), and 164 more.
Diseases named in the same sentence as ZNF471 in open-access papers:
ZNF471 is named in the same sentence as 29 diseases in open-access papers, as found by Europe PMC text mining. Sharing a sentence is not in itself a finding about the gene and the disease. The quoted sentences say what the papers report.
gastric cancer (10 papers, 2018 to 2024). A primary or metastatic malignant neoplasm involving the stomach. "ZNF471 has been reported to be downregulated or silenced by promoter hypermethylation in gastric cancer, squamous cell carcinoma of the tongue and esophageal, and low expression of ZNF471 is associated with poor survival." (PMID 33203470, 2020). "After adjustment of gender and TNM stage, hypermethylation of ZNF471 promoter (median value) was associated with poorer survival of gastric cancer patients (HR 2.315; 95% CI: 1.307–4.099; P = 0.004)." (PMID 29610526, 2018). "ZNF471 suppresses gastric cancer by transcriptionally repressing the PLS3 and TFAP2A downstream oncogenes." (PMID 39695171, 2024). "At the transcription level, zinc-finger protein 471 (ZNF471) suppressed the expression of TFAP2A in gastric cancer." (PMID 37291585, 2023). "The zinc-finger protein 471 was shown to inhibit gastric cancer progression through transcriptionally repressing downstream PLS3 and TFAP2A, suggesting that TFAP2A and PLS3 act as oncogenic factors in gastric cancer cell development." (PMID 36707053, 2023). "Chromatin immunoprecipitation (ChIP) assays in patients with gastric cancer have shown that the transcription factor ZNF471 acts as a tumor suppressor gene." (PMID 34023917, 2021). "Methylation of the CpG-methylation site of the ZNF471 promoter is a useful prognostic marker for overall survival in gastric cancer patients." (PMID 34023917, 2021). "ZNF471 acts as a tumor suppressor in gastric cancer by transcriptionally inhibiting downstream targets TFAP2A and PLS3." (PMID 33133131, 2020). "In paired primary gastric cancer samples from patients, the promoter methylation status of ZNF471 by BGS was significantly higher in tumor than adjacent normal tissues." (PMID 29610526, 2018). "With 120 gastric cancer patients, we evaluated the potential clinical impact of ZNF471 promoter methylation using a region harboring eight CpG sites." (PMID 29610526, 2018). "To understand the functional role of ZNF471 in gastric cancer migration and invasion, we performed wound healing and Matrigel invasion assay." (PMID 29610526, 2018). "Restored mRNA expression of ZNF471 was observed, indicating that DNA hypermethylation at ZNF471 promoter region is involved in its transcriptional silencing in gastric cancer." (PMID 29610526, 2018). "After stratification by TNM stage, gastric cancer patients with high CpG3 methylation in ZNF471 promoter demonstrated significantly shorter survival in stage III/IV (P = 0.003), but not in stage I/II." (PMID 29610526, 2018). "In conclusion, ZNF471 acts as a tumor suppressor in gastric cancer by transcriptionally inhibiting downstream targets TFAP2A and PLS3." (PMID 29610526, 2018). "Here we elucidated the functional significance, molecular mechanisms and clinical impact of ZNF471 in gastric cancer." (PMID 29610526, 2018). "ZNF471 promoter CpG-site hypermethylation correlated with poor survival of gastric cancer patients (n = 120, P = 0.001)." (PMID 29610526, 2018). "To investigate the functional role of ZNF471 in gastric cancer, we overexpressed ZNF471 in AGS, BGC823, and MKN74." (PMID 29610526, 2018). "Results demonstrated that DNA methylation of ZNF471 promoter was significantly higher in gastric cancer compared with paired adjacent tissues." (PMID 29610526, 2018). "Taken together, our results indicated for the first time that ZNF471 functions as a tumor suppressor in gastric cancer." (PMID 29610526, 2018). "Taken together, KAP1 serves as a co-repressor for ZNF471 in gastric cancer, inducing elevated H3K9me3 in the promoter of TFAP2A and PLS3." (PMID 29610526, 2018). "A series of in vitro and in vivo functional experiments revealed that ZNF471 possesses a tumor-suppressive function in gastric cancer." (PMID 29610526, 2018). "Zinc-finger protein 471 (ZNF471) was preferentially methylated in gastric cancer using promoter methylation array." (PMID 29610526, 2018).
gastric cancer (continued). "To ascertain the clinical importance of ZNF471, we analyzed 120 gastric cancer patients for the methylation status of an 8-CpG-site region in ZNF471 promoter." (PMID 29610526, 2018). "We found that the mRNA expression of ZNF471 was downregulated in 15 out of 16 gastric cancer cell lines, and the silenced ZNF471 expression was subsequently restored following treatment with a DNA methyltransferase activity inhibitor." (PMID 29610526, 2018). "Significantly higher ZNF471 promoter methylation was also observed in primary gastric cancers compared to their adjacent normal tissues (P < 0.001)." (PMID 29610526, 2018). "In summary, ZNF471 is a novel tumor suppressor in gastric cancer, inhibiting cell growth, triggering apoptosis and cell cycle arrest as well as impairing cell migration and invasion abilities." (PMID 29610526, 2018). "Enhanced gastric cancer cell colony formation ability due to ZNF471 knockdown by shRNA was abolished through further knocking down of TFAP2A, indicating that the tumor-suppressive effect of ZNF471 is partially dependent on TFAP2A suppression." (PMID 29610526, 2018). "Taken together, hypermethylation of ZNF471 functioned as an independent marker for poor gastric cancer prognosis." (PMID 29610526, 2018). "Ectopic expression of ZNF471 in silenced or low-expression gastric cancer cell lines (AGS, BGC823, and MKN74) inhibited cell proliferation and colony formation, induced apoptosis and arrested cells at G0/G1 phase." (PMID 29610526, 2018). "Among all, CpG3 of ZNF471 promoter had the predominant prognostic role for gastric cancer patients with the most significant P value (HR 2.616; 95% CI: 1.491–4.590; P = 0.001)." (PMID 29610526, 2018). "Both mRNA and protein expression of ZNF471 were silenced or downregulated in 15 out of 16 gastric cancer cell lines, while it was detected in MKN1, GES1 (a normal gastric epithelia cell line) as well as normal gastric tissue." (PMID 29610526, 2018). "Ectopic expression of ZNF471 in gastric cancer cell lines (AGS, BGC823, and MKN74) significantly suppressed cell proliferation, migration, and invasion, while it induced apoptosis in vitro and inhibited xenograft tumorigenesis in nude mice." (PMID 29610526, 2018). "Comparison of clinicopathological features between patients with high and low ZNF471 methylation revealed that high methylation level of ZNF471 positively correlated with gastric cancer metastasis (P = 0.0039)." (PMID 29610526, 2018). "To estimate the clinical importance of promoter methylation level of ZNF471 in gastric cancer, we quantified the DNA methylation level of CpG sites in ZNF471 promoter in paired gastric tumors and tumor adjacent tissues by BGS." (PMID 29610526, 2018). "ZNF471 mRNA was silenced in 15 out of 16 gastric cancer cell lines due to promoter hypermethylation." (PMID 29610526, 2018). "It has been reported that ZNF471 can block the proliferation and invasion of gastric cancer cells." (PMID 32489316, 2020). "ZNF471 has exhibited tumor-suppressive activities in gastric cancer and esophageal cancer." (PMID 32489316, 2020). "Hence, in this study, we elucidated the expression profile, epigenetic regulation, biological function, downstream effectors, promoter co-regulator, and clinical impact of ZNF471 in gastric cancer." (PMID 29610526, 2018). "ZNF471 is a transcription factor preferentially silenced by DNA methylation in gastric cancer, thus the dysregulation of ZNF471 may affect multiple cellular processes involved in its transcriptional regulation." (PMID 29610526, 2018). "As a member of KRAB-ZFP family, the role of ZNF471 in human gastric cancer is unclear." (PMID 29610526, 2018). "Hence, ZNF471 suppressed gastric cancer progression by transcriptionally repressing its downstream targets TFAP2A and PLS3 in co-operating with KAP1." (PMID 29610526, 2018).
gastric cancer (continued). "In addition to repressing cell proliferation, ZNF471-triggered gastric cancer cell apoptosis, with a significant increase in total apoptosis proportion (about 6% in AGS, 3% in BGC823, and 8% in MKN74, respectively)." (PMID 29610526, 2018). "Moreover, the re-expression of ZNF471 in gastric cancer cell lines (BGC823 and MKN74) significantly inhibited their migration and invasion abilities." (PMID 29610526, 2018). "Frequent methylation of ZNF471 in cancer has been reported in colorectal and squamous cell carcinoma 25, 26, and its biological functions have been reported to be involved in the regulation of cell proliferation, apoptosis, migration and invasion, as a tumor suppressor in gastric cancer." (PMID 32089740, 2020). "Combining the EMSA result and GSEA with TCGA Stomach Cancer gene expression RNAseq data, we identified TFAP2A and PLS3, as the critical targets of ZNF471." (PMID 29610526, 2018). "Immunofluorescence staining showed that ZNF471 localized in the nucleus of gastric cancer cell lines (AGS and BGC823) with ectopic expression of ZNF471, supporting its potential role as a transcriptional regulator." (PMID 29610526, 2018).
cervical cancer (4 papers, 2021 to 2023). A primary or metastatic malignant neoplasm involving the cervix. "Hypermethylation of the ZNF471 gene promoter and low ZNF471 expression was correlated with poor overall and recurrence-free survival in cervical cancer." (PMID 35281811, 2022). "ZNF471 suppresses cervical cancer cell invasion by modulating EMT via negative regulation of the Wnt/β-catenin signaling pathway." (PMID 35164660, 2022). "In another study, hypermethylation of the ZNF471 gene promoter was inversely correlated with its expression, and overexpression of ZNF471 inhibited EMT and acted as a tumor suppressor with diagnostic and prognostic significance in cervical cancer." (PMID 37779184, 2023). "A further example includes ZNF471, which acts as a tumor suppressor in cervical cancer." (PMID 35281811, 2022).
esophageal squamous cell carcinoma (4 papers, 2020 to 2023). Esophageal squamous cell carcinoma (ESCC) is a type of esophageal carcinoma (EC) that can affect any part of the esophagus, but is usually located in the upper or middle third. "ZNF471 was shown to be downregulated in esophageal squamous cell carcinoma (ESCC) cells, and restoration of expression leads to the induction of apoptosis and G0/G1 arrest, as well as inhibition of tumor cell colony formation." (PMID 34439859, 2021). "For example, in esophageal squamous cell carcinoma (ESCC), ZNF471 reduces cell growth via G0/G1 arrest, induces apoptosis, and reverses epithelial-to-mesenchymal transition (EMT), resulting in the inhibition of cell invasion and migration." (PMID 33672287, 2021). "The impact and mechanism of ectopic ZNF471 expression in esophageal squamous cell carcinoma (ESCC) cells was evaluated in vitro and in vivo." (PMID 32089740, 2020).
colorectal cancer (3 papers, 2014 to 2023). A primary or metastatic malignant neoplasm that affects the colon or rectum. "C ROC analysis for ZNF471 predicting aberrant methylation in colorectal cancer." (PMID 37779184, 2023). "Five hypermethylated genes including ZNF471, SND1, SPOCK1, FBLIM1, and OTX1 were detected and confirmed in 68 cases of colorectal cancer, 31 cases of adenoma, and 49 cases of normal control group." (PMID 37779184, 2023). "Our results indicated that ZNF471, SND1, SPOCK1, FBLIM1, and OTX1 methylation may be useful in diagnosing colorectal cancer and adenoma." (PMID 37779184, 2023). "The methylation degree of ZNF471 was more than 2.9-fold, SND1 was more than 14.5-fold, SPOCK1 was more than 5.8-fold, FBLIM1 was more than 11.1-fold, and OTX1 was more than 6.9-fold in colorectal cancer or colorectal adenoma to that in the normal control." (PMID 37779184, 2023). "Hypermethylated genes of ZNF471, SND1, SPOCK1, FBLIM1, and OTX1 were obtained from methylation chip detection and further confirm analysis in colorectal cancer and adenoma compared with normal tissue, which may be promising diagnostic markers of colorectal cancer and colorectal adenoma." (PMID 37779184, 2023). "Hypermethylated genes of ZNF471, SND1, SPOCK1, FBLIM1, and OTX1 were obtained from methylation chip detection and further confirm analysis in colorectal cancer and adenoma compared with normal tissue, which may be promising diagnostic markers of CRC and colorectal adenoma." (PMID 37779184, 2023).
tongue squamous cell carcinoma (3 papers, 2020 to 2023). A squamous cell carcinoma that arises from the tongue. "ZNF471 methylation was found in tongue squamous cell carcinoma and may be served as a diagnostic marker in the previous study." (PMID 37779184, 2023). "ZNF471 is methylated in squamous cell carcinomas of tongue, stomach and esophageal." (PMID 33203470, 2020).
breast carcinoma (2 papers, 2020 to 2024). "The molecular mechanisms underlying the tumor-suppressive functions of ZNF471 in breast cancer were further analyzed." (PMID 33203470, 2020). "Given that ZNF471 suppressed breast cancer cell proliferation in vitro, we further tested its function in vivo." (PMID 33203470, 2020). "In this study, we showed that ZNF471 was silenced or downregulated in breast cancer due to promoter methylation." (PMID 33203470, 2020). "In the present study, we found that ZNF471 was downregulated in six of nine breast cancer cell lines and 12 of 14 pairs of breast cancer tissues." (PMID 33203470, 2020). "Expression levels of ZNF471 in the transfected cells were examined by RT-PCR, qPCR, and western blotting.Colony formation and CCK-8 proliferation assays were performed to assess the effect of ZNF471 on cell proliferation in breast cancer." (PMID 33203470, 2020). "Taken together, ZNF471 suppressed breast cancer cell metastasis by attenuating the EMT and modulating MMPs." (PMID 33203470, 2020). "Consistently, the mRNA level of ZNF471 was significantly lower in 12 of 14 pairs of breast cancer tissues compared with paired surgical-margins." (PMID 33203470, 2020). "Results showed that ZNF471 methylation was far more prevalent in breast cancer tissues than in normal breast tissues, and downregulation of ZNF471 in breast cancer was significantly inversely correlated with its methylation." (PMID 33203470, 2020). "We assumed that the anti-cancer effect of ZNF471 in breast cancer was achieved by modulating AKT and Wnt/β-catenin signaling." (PMID 33203470, 2020). "To further demonstrate the tumor suppression function of ZNF471 in breast cancer, we knockdown of ZNF471 in ZNF471-expressing breast cancer cell line BT549 by siRNA transfection." (PMID 33203470, 2020). "To clarify the effect of ZNF471 in breast cancer, we first established cell lines that stably overexpress ZNF471." (PMID 33203470, 2020). "To assess whether ZNF471 is downregulated in breast tumors, we first examined the expression of ZNF471 in a panel of breast cancer cell lines, normal mammary epithelial cell lines (HMEC and HMEpC) and normal breast tissues by semiquantitative RT-PCR." (PMID 33203470, 2020). "Because the EMT plays an important role in cell migration and invasion by reducing cell–cell adhesion and increasing motility, we first tested whether ZNF471 inhibits breast cancer cell migration and invasion by attenuating the EMT." (PMID 33203470, 2020). "Furthermore, ZNF471 expression was associated with progesterone receptor (PR), HER2, nodal status and tumor grade of breast cancer." (PMID 33203470, 2020). "Thus, part of the mechanism of ZNF471 inhibition of breast cancer cell metastasis was attenuating the EMT." (PMID 33203470, 2020). "These knockdown data confirmed that ZNF471 has a tumor-suppressive effect on breast cancer." (PMID 33203470, 2020). "ZNF471 functions as a tumor suppressor that was epigenetically inactivated in breast cancer." (PMID 33203470, 2020). "In summary, ZNF471 as a TSG in breast cancer and often inactivated by promoter methylation." (PMID 33203470, 2020). "Therefore, the tumor-suppressive functions of ZNF471 in breast cancer were first investigated in this study." (PMID 33203470, 2020). "We thus investigated the functions of ZNF471 in breast cancer." (PMID 33203470, 2020). "Thus, ZNF471 suppressed breast cancer cell metastasis by attenuating the EMT." (PMID 33203470, 2020). "We next examined whether ZNF471 downregulation in breast cancer was due to promoter methylation." (PMID 33203470, 2020). "However, the role of ZNF471 in breast cancer remains unclear." (PMID 33203470, 2020). "ZNF471 was readily detected in HMEpC and HMEC cells, but dramatically reduced or silenced in six of nine breast cancer cell lines." (PMID 33203470, 2020).
breast carcinoma (continued). "ZNF471, a member of the KRAB C2H2-type ZFP family, was found to be silenced by promoter hypermethylation in gastric, colon, tongue squamous, oesophageal, and breast cancers 19-20, 25-27." (PMID 38169650, 2024). "We further performed the univariate and multivariate Cox regress analyses through analyzing breast cancer genomic data from the TCGA database (n = 639), however,we found that ZNF471 is not an independent predictor in breast cancer." (PMID 33203470, 2020). "Whether or not ZNF471 could modulate AKT and Wnt/β-catenin signaling in breast cancer was still unclear." (PMID 33203470, 2020).
esophageal cancer (2 papers, 2020 to 2022). A primary or metastatic malignant neoplasm involving the esophagus. "For example, ZNF471 is significantly hypermethylated and has low mRNA expression in esophageal cancer compared with that in normal tissues." (PMID 35164660, 2022). "Together, these results indicate that promoter CpG methylation of ZNF471 is a mechanism contributing to its downregulation or silencing in esophageal cancer." (PMID 32089740, 2020).